INS (insulin)
Diseases named in the same sentence as INS in open-access papers (continued):
Sharing a sentence is not in itself a finding about the gene and the disease.
type 1 diabetes (continued). "Despite widespread implementation of basal-bolus insulin regimens as the most adequate treatment for type 1 diabetes, there are large interindividual differences in the level of glycaemic control." (PMID 36394644, 2023). "When type 1 diabetes is diagnosed in an individual, it is with an artificial cut-off value of hemoglobin A1C levels and then a person is put on insulin treatment when there is insufficient insulin production." (PMID 38015167, 2023). "In a type 1 diabetic mouse model, this interface is demonstrated to ameliorate hyperglycemia by stimulating insulin expression." (PMID 37524785, 2023). "A previous study showed that in children with type 1 diabetes, positivity for ZnT8A at diagnosis correlated with low C-peptide levels 2 years later, which resulted in a higher daily insulin requirement in these patients." (PMID 37224769, 2023). "Another condition is hepatic resistance in children affected by poor-controlled type 1 diabetes (T1D), which is treated with insulin, resulting in the decrease of IGF-1 levels." (PMID 37008935, 2023). "The complex treatment for diabetes type 1 (T1D) includes insulin dosing for every meal, which requires education and experience to achieve optimal outcomes." (PMID 38004219, 2023). "Till now, there has been no comprehensive meta-analyses comparing the day and night time efficacy and safety features between traditional SAP therapy and the currently used CLC insulin delivery for pediatric and adolescents with type 1 diabetes." (PMID 37574494, 2023). "The use of cell therapies for the treatment of type 1 diabetes has focused on restoring physiological insulin production through regenerative or tissue engineering approaches to beta cell substitution." (PMID 37221247, 2023). "Proposed factors influencing adiponectin include insulin signaling impairments, as observed among patients with Type 1 Diabetes, and in animal studies that found dependence of adiponectin expression on T-cadherin and glycoprotein levels." (PMID 37653519, 2023). "Personalized insulin therapy is of utmost importance in managing type 1 diabetes, as it allows for tailoring treatment to the individual’s lifestyle, dietary habits, and exercise regimen." (PMID 37724233, 2023). "The cornerstone in the treatment of type 1 diabetes is to supply insulin, mimicking the physiologic endogenous insulin secretion as closely as possible." (PMID 38089060, 2023). "The type I diabetes appeared to stabilize after insulin treatment, and the keratoacanthoma gradually resolved after drug discontinuation." (PMID 37593095, 2023). "Here, we performed a full characterisation of oxPTM-INS and evaluated antibody and T cell responses towards insulin peptides (INSPs) generated by oxPTM in individuals with type 1 diabetes." (PMID 36207582, 2023). "In the study, the age of onset of type 1 diabetes, the time of initiation of insulin therapy, and the fasting C peptide level were measured." (PMID 37626799, 2023). "Type 1 diabetes is an autoimmune disease characterized by the destruction of insulin-producing β cells in the pancreas." (PMID 38125492, 2023). "Antibodies specific to oxidative post-translational modifications (oxPTM) of insulin (oxPTM-INS) are present in most individuals with type 1 diabetes, even before the clinical onset." (PMID 36207582, 2023). "Higher overall HbA1c levels are reported in AA children with type 1 diabetes compared to white children, after adjustment for socioeconomic status, diabetes duration, and insulin dose." (PMID 37216026, 2023). "Type 1 diabetes (T1D), being a multifactorial and autoimmune disease, is characterized by the destruction of pancreatic β cells by T cells, which results in a deficiency of the synthesis and secretion of insulin." (PMID 38201852, 2023). "Type 1 diabetes is an incurable disease that results from abnormalities in the insulin hormone level, which is responsible for controlling blood glucose levels." (PMID 36776951, 2023).
type 1 diabetes (continued). "Metabolic modelling of the data derived from standard tests such as the OGTT or MMTT provides a more accurate and convenient way to estimate both insulin secretion and insulin sensitivity in early-stage type 1 diabetes." (PMID 37712956, 2023). "This case report involves a 29-year-old male with a history of type I diabetes mellitus, schizophrenia, and a prior suicide attempt via insulin overdose." (PMID 37153266, 2023). "Treatment of type 1 diabetes centers on insulin administration to replace or supplement the body's own insulin with the goal of achieving euglycemia and preventing or minimizing complications." (PMID 37507704, 2023). "An insulin reservoir is a main component of an implantable AP, the latter currently considered to be the way forward for future treatment of Type-1 diabetes." (PMID 36976069, 2023). "In order to treat type 1 diabetes, the traditional method involves checking blood glucose levels manually, followed by daily subcutaneous insulin injections." (PMID 37266052, 2023). "Of striking significance, this significant improvement in residual functional β-cell mass, as evidenced by elevated basal and postprandial insulin secretion in the blood, persists in mothers with type 1 diabetes for up to 8 weeks in the postpartum phase." (PMID 38229396, 2023). "Alloxan administration induces a pattern similar to human type 1 diabetes due to its selective damage to the pancreatic β-cells in the islets of Langerhans that produce insulin." (PMID 36674892, 2023). "Type I diabetes mellitus (T1D) is defined by the autoimmune destruction of pancreatic β‐cell mass, and its management is centered on insulin replacement, maintaining tissue sensitivity to insulin and glucose homeostasis." (PMID 37568265, 2023). "A group of 26 patients of type 1 diabetes with conventional treatment of insulin injections was put as a control group in the same period." (PMID 37663700, 2023). "Stricter outcome definitions for type 1 diabetes diagnosis or insulin prescription showed comparable results to the primary analysis." (PMID 37080595, 2023). "Circulating C-peptide levels, derived from sustained endogenous insulin secretion, provide an indication of preserved beta cell mass, and their decline signifies disease progression in individuals with type 1 diabetes." (PMID 37537394, 2023). "Exogenous insulin administration exposes individuals with type 1 diabetes to marked glycaemic fluctuations." (PMID 36871019, 2023). "A real-time prototype of a perfusable pancreas-on-a-chip model was tested for type 1 diabetes, which comprised anastomosing micro-capillaries developed from rodent pancreatic islets for insulin secretion." (PMID 37109483, 2023). "Type 1 diabetes mellitus (T1D) is understood to be an autoimmune disease: an immune system-induced destruction of the insulin-producing cells in the pancreas leading to absolute insulin deficiency." (PMID 37408713, 2023). "Insulin-producing β cells created from human pluripotent stem cells have potential as a therapy for insulin-dependent diabetes, but human pluripotent stem cell-derived islets (SC-islets) still differ from their in vivo counterparts." (PMID 37188763, 2023). "Glucose insufficiency owing to insulin-induced hypoglycemia, an unremitting complication of type I diabetes mellitus management, can injure or destroy brain neurons." (PMID 36829519, 2023). "Type 1 diabetes is a chronic autoimmune condition, where the immune system destroys the pancreatic beta cells producing insulin." (PMID 37597078, 2023). "Adiponectin lowers inflammatory responses and promotes insulin sensitivity and is associated with lower risk of CVD in adults with type 1 diabetes." (PMID 40303256, 2023). "The type 1 diabetes is mostly related to autoimmune destruction of pancreatic β-cells resulting in absolute or near absolute failure of insulin production and secretion." (PMID 37434784, 2023).
type 1 diabetes (continued). "In this study, rats developed glycogenic hepatopathy similar to those in type 1 diabetes after resuscitation and insulin overdose." (PMID 38250973, 2023). "Being female (β = -5.42, 95%CI:-8.63,-2.21, p = 0.001) and treated for type-I diabetes mellitus (β = + 9.04, 95%CI: 4.23,13.85, p-value < 0.0001) were significantly associated with HRQOL of patients on insulin therapy." (PMID 37143082, 2023). "Automated insulin delivery systems, also known as closed-loop or ‘artificial pancreas’ systems, are transforming the management of type 1 diabetes." (PMID 37289734, 2023). "This brings challenges like the scarcity of appropriate methods to evaluate adherence to insulin treatment or variations in recommended blood glucose monitoring frequencies for patients with type 1 diabetes." (PMID 36574148, 2023). "Its levels are elevated in patients with type 1 diabetes, particularly during the early stages of the disease, contributing to the inflammatory response that leads to the destruction of insulin-producing β cells in the pancreas." (PMID 37409229, 2023). "People with type 1 diabetes and a history of poor glycemic control present a rapid improvement in glycemic control, usually due to insulin treatment." (PMID 37513978, 2023). "Here, we propose a model of glucose-insulin regulation that captures the effects of exercise on glucose metabolism and personalize it to individual children with type 1 diabetes, allowing subject-specific treatment assessment." (PMID 36791144, 2023). "We also report that 13% of patients with type 1 diabetes in our registry use adjuvant glucose-lowering therapy in addition to insulin, significantly higher than the 5.4% reported from the T1D Exchange Registry in the US." (PMID 37505282, 2023). "Type 1 diabetes (T1D) is a chronic autoimmune disease, in which autoreactive T cells mediate the progressive destruction of insulin-producing beta cells in the pancreas." (PMID 37415982, 2023). "In recent years, medical-technical aids such as continuous glucose monitoring and insulin pumps, which facilitate the dosing adjustments in type 1 diabetes therapy, have become widespread among children and adolescents in Germany." (PMID 37408713, 2023). "Two recent studies have reported a relatively low incidence of nocturnal hypoglycaemia after aerobic exercise in people with type 1 diabetes using insulin degludec." (PMID 36879098, 2023). "Human insulin-producing immortalized EndoC-βH5 cells are cocultured with human endothelial cells in varying ratios to evaluate 3D cell culture models for type 1 diabetes research." (PMID 38162632, 2023). "In type 1 diabetes (insulin-dependent), the chronic autoimmune process leads to the gradual destruction of the insulin-producing β cells of the pancreas." (PMID 37298479, 2023). "Type 1 diabetes, also known as juvenile diabetes, is an autoimmune disorder in which the body’s immune system attacks and destroys the cells that produce insulin, a hormone that regulates blood sugar levels." (PMID 37784049, 2023). "Diabulimia is a disordered eating behavior in which a person with type 1 diabetes withholds insulin injections to lose weight." (PMID 38041170, 2023). "They concluded that the death of pancreatic cells leads to the inhibition of insulin secretion and, therefore, the development of type-1 diabetes." (PMID 36901457, 2023). "In Italy, a survey in 2020 showed that only 18,1% of adults with type 1 diabetes were using an insulin pump." (PMID 36801976, 2023). "In type 1 diabetes (T1D), the patient’s own insulin-producing β-cells are specifically destroyed through an autoimmune-mediated attack predominantly of T-cells, resulting in insulin deficiency." (PMID 36899834, 2023). "At the present time, multiple daily injections (MDI) of insulin are the current standard treatment for type 1 diabetes." (PMID 37685946, 2023).
type 1 diabetes (continued). "Many studies have suggested that leptin can be used as an antidiabetic drug or in addition to insulin therapy in patients with insulin-dependent diabetes." (PMID 37670877, 2023). "Another similar effect observed in a previous study was that the unsupervised usage of an educational game, "L'Affaire Birman", was able to improve insulin titration and carbohydrate quantification results for children with type 1 diabetes." (PMID 37340334, 2023). "T2DM, also known as non-insulin-dependent diabetes, results in a defect in the insulin secretion pathway that leads to insufficient insulin secretion and production." (PMID 37943820, 2023). "For example, in the family planning data dictionary, WHO recommendations use the term ‘insulin/non-insulin dependent diabetes’, due to the potential interactions between insulin and hormonal contraception." (PMID 37562854, 2023). "As autoantibody testing was negative and c-peptide level demonstrated significant endogenous insulin secretion, type 1 diabetes was excluded." (PMID 37855645, 2023). "This study aimed to assess the gingival crevicular fluid (GCF) microbiome and metabolome of adults with type 1 diabetes (T1D) treated with continuous subcutaneous insulin infusion (CSII)." (PMID 38371896, 2023). "Our primary outcome will be the proportion of people with type 1 diabetes and an HbA1c above 69 mmol/mol who start and continue insulin pump use during the 18-month intervention period." (PMID 37653413, 2023). "Summary of studies reporting the C-peptide levels and the assessment of endogenous insulin secretion in type 1 diabetes in sub-Saharan Africa." (PMID 36778553, 2023). "Although insulin is only one of many type 1 diabetes-relevant autoantigens, several lines of evidence suggest that insulin autoreactivity, both in mice and humans, plays a key role in the initiation of type 1 diabetes." (PMID 37488322, 2023). "From that moment, patients with type 1 diabetes rely on a combination of exogenous insulin administration, healthy diet and regular physical activity to achieve optimal glycemic control." (PMID 38033011, 2023). "Type 1 diabetes (T1D) is a T lymphocyte mediated autoimmune disease that leads to the destruction of insulin producing beta cells within the pancreatic islets of Langerhans." (PMID 37903947, 2023). "In children with type 1 diabetes, serum irisin concentration was positively correlated with bone mass and glycemic control after continuous subcutaneous insulin infusion." (PMID 35002510, 2022). "Among six patients with type 1 diabetes, a dataset containing insulin dose, carbohydrate intake, and glucose levels for 8 weeks was used to train and benchmark a blood glucose forecasting model based on casual dilated CNN." (PMID 35646863, 2022). "Intensive insulin therapy used in children with type 1 diabetes allows to maintain near-normoglycaemia and thus avoid long-term complications of the disease, what is the primary purpose of treatment." (PMID 35784568, 2022). "Patients with type 1 diabetes are currently treated with either multiple daily insulin injections (MDI) or insulin pumps." (PMID 35757419, 2022). "Destruction of beta cells leads to a decrease in insulin secretion, development of hyperglycemia, and ultimately clinical type 1 diabetes." (PMID 35330341, 2022). "The current study helps to obtain a comprehensive picture of the availability of insulin pumps among type 1 diabetes in clinical practice in China." (PMID 35757419, 2022). "Type 1 diabetes (T1DM) is a chronic disease requiring lifelong insulin therapy and rigorous self-management." (PMID 36130979, 2022). "Patients with type 1 diabetes cannot produce endogenous insulin and thus require treatment with exogenous insulin." (PMID 35156937, 2022). "Most individuals with type 1 diabetes should be treated with multiple daily injections of insulin or a continuous infusion of subcutaneous insulin." (PMID 36556420, 2022).
type 1 diabetes (continued). "Type 1 diabetes patients should be educated on how to match their mealtime insulin doses to their carbohydrate intake, fat and protein content, and anticipated physical activity." (PMID 36556420, 2022). "Insulin-producing cells derived from induced pluripotent stem cells (iPSCs) are promising candidates for β cell replacement in type 1 diabetes." (PMID 36077097, 2022). "Type 1 diabetes is classified as an autoimmune disorder in which the body destroys insulin-producing pancreatic beta cells leading to an insulin deficiency, which also includes latent autoimmune diabetes in adulthood." (PMID 36012526, 2022). "Over 90% of people with newly diagnosed type 1 diabetes have measurable serum antibodies against specific β-cell proteins, including insulin (IAA), glutamate decarboxylase (GADA), islet antigen 2 (IA2A), zinc transporter 8 (ZnT8A)." (PMID 35769090, 2022). "In the context of the pathogenesis of type 1 diabetes, blood glucose levels began to rise when β cell destruction resulted in insufficient insulin production to regulate glucose uptake." (PMID 36250460, 2022). "In the beginning, as the fasting blood glucose rate was assumed to be matched with uncontrolled type-1 diabetes, the inputs confront jumps in insulin rate to compensate for high blood glucose levels as soon as possible." (PMID 35851835, 2022). "We present a case in which transition to a closed-loop hybrid insulin pump system, followed by significant improvement in glycemic control, led to development of insulin edema in a person with type 1 diabetes." (PMID 36180933, 2022). "In vivo experiments exhibited remarkable bioavailability of INS and an ideal glucose homeostasis in the type I diabetic rat model." (PMID 35248067, 2022). "Today, a century later, inadequate access to insulin translated into an average lifespan for a child with type I diabetes as short as 1 year in the sub-Saharan African region." (PMID 35431962, 2022). "Little is known about the application of insulin pumps among patients with type 1 diabetes in China." (PMID 35757419, 2022). "The patient’s immune system attacks and destroys insulin-producing cells in the pancreas in type 1 diabetes." (PMID 36143293, 2022). "Accordingly, health care providers can focus on the benefits of multiple daily injections and insulin pumps in treatment of patients with type 1 diabetes." (PMID 36443739, 2022). "This review will outline why pancreatic transcription factors have been utilised and how their application can allow the development of insulin-producing cells from non β-cells and potentially act as a cure for type 1 diabetes." (PMID 35883588, 2022). "In type 1 diabetes, dysfunctional glucose regulation occurs due to the death of insulin-producing beta-cells in the pancreatic islets." (PMID 36291702, 2022). "All patients were divided into subgroups: those of type 1 diabetics received water 5 ml, insulin 5 IU/prescribed dose, or crude fresh slices A. cepa 100 g whereas those of T2DM subjects taken water 5 ml, glibenclamide 5 mg, or crude fresh slices A. cepa 100 g." (PMID 35912631, 2022). "More than 1 in 4 patients in the United States with type 1 diabetes reported rationing their insulin in 2019." (PMID 35156937, 2022). "Repeated subcutaneous injections of insulin disturbs the lives of patients with insulin-dependent diabetes." (PMID 35384787, 2022). "Insulin represents a life-saving treatment in patients with type 1 diabetes, and technological advancements have improved glucose control in an increasing number of patients." (PMID 36073717, 2022). "Classically, type 1 diabetes has been viewed as a disease of the immune system present prior to dysglycemia, with autoimmune biomarkers, islet autoantibodies directed against insulin and, other beta cell proteins." (PMID 36497105, 2022). "Significant progress has been made in the personalisation of type 1 diabetes treatment since the discovery of insulin in 1922." (PMID 35994083, 2022).